IL6 (interleukin 6)
Diseases named in the same sentence as IL6 in open-access papers (continued):
Sharing a sentence is not in itself a finding about the gene and the disease.
rheumatoid arthritis (continued). "IL-6 induces the ERK pathway to regulate the differentiation and activation of T lymphocytes and is a cytokine that has recently been targeted for treating chronic inflammatory diseases such as asthma and rheumatoid arthritis." (PMID 32963561, 2020). "Moreover, another study showed that blocking of TNF-α markedly reduced the levels of IL-6, IL-1β, and IL-17 in patients with rheumatoid arthritis, indicating that Th17 cell differentiation is promoted by TNF-α through IL-6 and IL-1β." (PMID 33204736, 2020). "The inhibitory effects of IL-6 in osteoblast differentiation in rheumatoid arthritis are due to its negative interaction with the Wnt pathway." (PMID 33234152, 2020). "For example, IL-6 and its receptor IL-6R monoclonal antibody have been used in the treatment of rheumatoid arthritis and uveitis, and JAK small molecule inhibitors have also been used in the treatment of rheumatoid arthritis and myelofibrosis." (PMID 33384595, 2020). "Moreover, it has been documented that over-expression of miR-99b-5p brings about elevations in the expression levels of proinflammatory cytokines (IL-2, IL-6, TNFα, and IFN-γ), thus promoting the pathogenesis of rheumatoid arthritis." (PMID 33109608, 2020). "Genistein was also shown to suppress the expression of IL-1β, IL-6, and TNF-α in the serum, which indicates that it could have the potential to improve symptoms of rheumatoid arthritis in rats." (PMID 31137797, 2019). "IL-6 knock-out mice are protected from development of experimental autoimmune encephalomyelitis (EAE), the mouse model of human multiple sclerosis and mouse models of rheumatoid arthritis." (PMID 31694340, 2019). "miR-124-mediated inhibition of IL-6 signaling, provides a novel explanation for VD's role on T cells in CIA mice or RA patients and suggests that VD may have treatment implications in rheumatoid arthritis." (PMID 30792721, 2019). "Also, in synovial fibroblasts from the temporomandibular joint of patients with rheumatoid arthritis, celecoxib reduced COX-2 and IL-6 expression by suppression of PG-E2 synthesis during stimulation of cells with PG-E2/IL-1β." (PMID 30983880, 2019). "This may result from decreased IL-6 seen in PTX+TCDD treated mice because IL-6-mediated STAT3 signaling is essential for Th17 differentiation and plays a central role in the pathogenesis of certain autoimmune diseases such as rheumatoid arthritis." (PMID 31681214, 2019). "In models of human immune cells in culture, selected for their relevance to the pathogenesis of rheumatoid arthritis, CR6086 markedly decreased PGE2-mediated IL-23 release from human dendritic cells, IL-17 release from human Th17 cells, and IL-6 and VEGF transcription in human macrophages." (PMID 29490676, 2018). "Furthermore, IL-6 and TNF exert potent systemic effects that help drive some of the co-morbidities seen in rheumatoid arthritis, including altered cholesterol metabolism, atherosclerosis and even mood disturbance [27▪]." (PMID 29206659, 2018). "The objective of the present study was to evaluate the effects of Enalapril, Losartan and Valsartan on the production of IL-2, IL-10, IL-6, TNF, IFN-γ, IL-17A, IL-17F and IL-22 cytokines in PBMCs of patients with rheumatoid arthritis and evaluate this modulation with disease activity." (PMID 30288187, 2018). "Although IL-6 specific treatments (e.g. tocilizumab) have been developed, but not yet tried as a treatment for COPD, one case report describes worsening of emphysema during treatment for rheumatoid arthritis." (PMID 29065892, 2017). "Current IL-6 blockade treatments, used in specific inflammatory diseases, such as rheumatoid arthritis, are nonspecific (targeting both IL-6 classic and trans-signaling) and are associated with increased infection and metabolic disturbances." (PMID 28250574, 2017).
rheumatoid arthritis (continued). "Since simultaneous inhibition of both the p38MAPK and ERK-MSK-CREB pathways are required to significantly reduce LPA-mediated IL-8 and IL-6 production in TNFα-preconditioned RAFLS, drug combinations targeting these two pathways are potential new strategies to treat rheumatoid arthritis." (PMID 29209219, 2017). "In rheumatoid arthritis, resistin has been shown to accumulate within inflamed joints, and to correlate with the degree of inflammation and the expression of inflammatory cytokines including TNF-α, IL-1β and IL-6." (PMID 28642544, 2017). "Some groups had reported that mice with rheumatoid arthritis receiving MSCs were less likely to show signs of joint inflammation than those not receiving MSCs by decreasing proinflammatory cytokines such as TNF-α and IL-6." (PMID 29096724, 2017). "Similar findings have been reported in that although tocilizumab treatment decreased TNF-α and IL-1β levels, serum IL-6 levels were increased by tocilizumab therapy regardless of the improvements in clinical measures in rheumatoid arthritis patients." (PMID 27068103, 2016). "Similarly, CoQ10 has also been observed to inhibit the expression of IL-6, TNF-α and NF-κB, an anti-inflammatory effect mediated via gene expression modification or antioxidant/radical-scavenging activity in Rheumatoid Arthritis Patients33." (PMID 27452860, 2016). "Blockade of granulocyte macrophage colony-stimulating factor (GM-CSF) and its receptor (GM-CSFRα) is being successfully tested in trials in rheumatoid arthritis (RA) with clinical results equivalent to those found with neutralization of the current therapeutic targets, TNF and IL-6." (PMID 27908288, 2016). "IL-6 directly inhibited proliferation of burst-forming units-erythroid (BFU-E) and colony-forming units-erythroid (CFU-E) in bone marrow cultures from healthy donors and from rheumatoid arthritis patients." (PMID 27068103, 2016). "Like other pro-inflammatory cytokines such as TNFα and IL-1β, IL-6 is an important therapeutic target of immune disorders, and anti-IL-6 receptor antibody, tocilizumab, has been developed as a therapy in human diseases, including rheumatoid arthritis (RA) and Castleman’s disease." (PMID 27070121, 2016). "The estrogen deficient menopausal problems lead to an increase in the progression of cytokines such as GM-CSF, IL-1, and IL-6, and that could potentially induce autoimmune responses in systemic autoimmune diseases such as SLE and rheumatoid arthritis." (PMID 26294906, 2015). "IL-6 inhibitors are available in the clinic for suppression of inflammation in rheumatoid arthritis, where they seem to be osteoanabolic, rather than catabolic." (PMID 25712618, 2015). "Accumulating evidences demonstrated that visfatin was identified as a proinflammatory adipocytokine and secreted extracellularly to upregulate inflammatory cytokines, such as TNF-α, IL-1β, IL-6 and CCL2 in rheumatoid arthritis synovial fibroblasts and monocytes in response to inflammatory stimuli." (PMID 25993304, 2015). "Interestingly, when the concentration of 4-HNE increased to 50 μM, the mRNA levels of IL1-β, IL-6, and TNF-α in rheumatoid arthritis synovial cells increased gradually with the increasing time up to 1 h and then decreased." (PMID 25741130, 2015). "Interleukin‐6 (IL‐6) may play a pathological role in rheumatoid arthritis (RA) and periodontitis." (PMID 29744142, 2015). "Anti-interleukin-6 therapy was safely used in this patient with rheumatoid arthritis without exacerbations of multiple sclerosis." (PMID 25216562, 2014). "Although the etiologies of rheumatoid arthritis (RA) are not fully understood, proinflammatory cytokines such as tumor necrosis factor- (TNF-) α, interleukin- (IL-) 1, and IL-6 have been shown to play a role in the pathology of RA and, as such, are potential therapeutic targets." (PMID 24872899, 2014).
rheumatoid arthritis (continued). "The expression of RANKL, JAK2, STAT3, and SOCS3 proteins was assessed by western blot analysis, real-time PCR and ELISA in IL-6 combined with soluble IL-6 receptor (sIL-6R)-stimulated rheumatoid arthritis (RA)-FLS with or without tacrolimus treatment." (PMID 23406906, 2013). "This antigen nonspecific affection of T cell function is in agreement with data showing that impaired regulation of inflammatory cytokines like IL-6 maintains pathologic Teff activation in rheumatoid arthritis independent of T cell antigen specificity." (PMID 24155968, 2013). "Aberrant DNA methylation has also been implicated in rheumatoid arthritis (RA), with reduced DNA methylation reported in peripheral blood mononuclear cells (PBMC), T cells and synovial cells, including at a specific CpG site at the gene encoding the pro-inflammatory cytokine IL6." (PMID 23148518, 2012). "Rheumatoid arthritis (RA) is a multifactorial chronic inflammatory joint disease that involves secretion of proinflammatory cytokines such as tumour necrosis factor-α (TNF-α), interleukin 1 (IL-1), and IL-6 which are associated with local inflammation and a systemic reaction." (PMID 19946428, 2009). "Emerging clinical data also link sustained IL-6 suppression to transient vagal hypoactivity: heart rate variability (HRV), a key measure of parasympathetic function, inversely correlates with inflammatory markers such as IL-6 and CRP in patients with rheumatoid arthritis." (PMID 40977707, 2025). "However, the elevated levels of IL-6 are observed in some but not all patients with rheumatoid arthritis, and there was not always a direct correlation with the increased levels of TNF-α, IL-1, or other proinflammatory cytokines." (PMID 40332498, 2025). "In rheumatoid arthritis (RA), the CD27 IgD naïve B cell subset produces IL-6, and both HIF-1α and IL-6 are co-expressed in RA patient B cells." (PMID 40791591, 2025). "In conditions like systemic lupus erythematosus (SLE) and rheumatoid arthritis (RA), PANoptosis in innate immune cells (e.g., dendritic cells) may promote the release of self‐antigens, disrupt immune tolerance, and exacerbate inflammation via signaling pathways such as IL‐6/JAK‐STAT3." (PMID 40613560, 2025). "To further verify the expression of LOXL1 in rheumatoid arthritis synovium, we used TNF-α to stimulate human osteosarcoma synovial cells for 48 h, extracted total protein and total mRNA, and detected the expression of LOXL1, INOS, COX2, and IL-6 in them through RT-qPCR and western blot." (PMID 38217541, 2024). "In rheumatoid arthritis (RA), fibroblasts activated by tumor necrosis factor (TNF) produce high levels of chemokines such as IL-6, CXCL12, and CCL2, which enhance the recruitment and attraction of monocytes." (PMID 39290699, 2024). "Finally, even some authors reported that azathioprine does not modify the levels of IL-6 in rheumatoid arthritis patients; we found that IL-6 levels were higher when azathioprine was not prescribed." (PMID 39456842, 2024). "EA alleviates the inflammatory reaction by reducing the levels of serum pro-inflammatory cytokines such as IL-1, IL-1β, IL-6, IL-17, IL-23, and TNF-α in rheumatoid arthritis (RA) animal models and IL-17 in the peripheral blood of RA patients." (PMID 39335365, 2024). "Immunological diseases such as rheumatoid arthritis (RA), as described in this case, induce chronic inflammation mediated by cytokines (e.g., TNF-α, IL-6), degrading the extracellular matrix of the sclera and increasing susceptibility to trauma." (PMID 39949387, 2024). "In the development of rheumatoid arthritis (RA), TNF-α, IL-1, IL-6, IL-2 and many other inflammatory factors mediate the inflammatory response." (PMID 38629066, 2024). "Notably, by the 48th hour, the serum TNF‐α and IL‐6 levels in the ACS group without rheumatoid arthritis had decreased to levels comparable to those of the controls." (PMID 39669190, 2024).
rheumatoid arthritis (continued). "The pathophysiology of rheumatoid arthritis (RA) involves the contribution of cytokines, specifically TNF-α, IL1-β, IL-6, and IL-8, which play significant roles in the process of synovial inflammation and joint destruction by inducing MMP expression." (PMID 38254696, 2024). "A recent publication described the development of bispecific nanobodies targeting IL-6 and TNF with additive efficacy in translational models of rheumatoid arthritis by inhibition of classic and trans-signaling of IL-6 and TNF signaling, a strategy that most likely will not work in IBD." (PMID 37838173, 2023). "In vitro experiments have shown that the JBQG drug serum can inhibit the expression of cytokines (IL-6, IL-8, IL-22, IL-23), chemokine proteins and mRNA expression (MMP-1, MMP-2, MMP-3, MMP-9, MMP-13) in rheumatoid arthritis synovial fibroblasts (RA-FLS)." (PMID 37180723, 2023). "In rheumatoid arthritis (RA), CD36 expression in fibroblasts is increased by macrophage-derived inflammatory mediators, including interleukin-1β (IL-1β), IL-6 and interferon gamma (IFN-γ)." (PMID 37576819, 2023). "Tocilizumab, a humanized anti-IL-6 R monoclonal antibody, for example, was the first drug to successfully block the IL-6 signal and was licenced by the US Food and Drug Administration (FDA) for the treatment of rheumatoid arthritis, systemic juvenile idiopathic and giant cell arteritis." (PMID 37343193, 2023). "Similarly, in the rheumatoid-arthritis (RA) joint, activated MCs release pro-inflammatory and immunomodulatory mediators (TNF-A, IL-6, IL-8, VEGF, histamine, heparin, tryptase) that induce angiogenesis, promote cartilage erosions, synoviocyte proliferation, and pain sensitization." (PMID 36291664, 2022). "The treatment of rheumatoid arthritis (RA) has advanced from the use of steroids to disease-modifying anti-rheumatic drugs (DMARDs) and biologics such as tumor necrosis factor (TNF) and interleukin-6 (IL-6) inhibitors." (PMID 36168347, 2022). "The therapeutic benefit of neutralizing the effects of IL-6 has already been suggested for several autoimmune diseases including systemic lupus erythematosus (SLE) and rheumatoid arthritis (RA)." (PMID 36389698, 2022). "Therefore, treatment strategies focused on the IL-6 pathway have been researched in various areas such as cancer, inflammation, and autoimmune diseases; in fact, anti-IL6 therapy is available for Castleman disease and rheumatoid arthritis." (PMID 36012469, 2022). "In vivo rat model of rheumatoid arthritis (RA), DEX suppresses NLRC5, therefore reducing cytokine levels of IL-1β, IL-6, IL-17A, and TNF-α." (PMID 35628263, 2022). "Resveratrol has shown anti-rheumatoid arthritis properties by decreasing rheumatoid arthritis patients’ swelling, tenderness and disease activity via decreasing the biochemical markers of inflammation such as MMP-3, ESR, C-reactive protein, IL-6 and undercarboxylated osteocalcin." (PMID 36551806, 2022). "Given the mechanistic rationale for the role of IL-6 signaling in T1D and that other effective rheumatoid arthritis drugs (abatacept and TNF-α blockers) have shown benefit in T1D, we hypothesized that blockade of the IL-6 pathway with tocilizumab would lead to clinical improvements in T1D." (PMID 34747368, 2021). "Although one study indicated that IL-6 did not play a major role in the inflammatory response in this model, it is still considered as a key inflammatory mediator in the pathogenesis of rheumatoid arthritis." (PMID 34950033, 2021).
rheumatoid arthritis (continued). "Rheumatoid arthritis (RA) is a chronic autoimmune disease characterized by joint destruction; cytokines such as tumor necrosis factor-α (TNF-α) and interleukin-6 (IL-6) play key roles in systemic inflammation." (PMID 33658620, 2021). "To determine whether IL-1β and IL-6 response modules were able to detect elevated cytokine bioactivity in vivo, we assessed the blood transcriptome of juvenile idiopathic arthritis (JIA) and rheumatoid arthritis (RA) patients." (PMID 33319166, 2021). "At present, the anti-IL-6 antibody tocilizumab, which is used to treat rheumatoid arthritis, is not indicated for asthma, but basic experiments suggested that IL-6 may be an important marker of asthma." (PMID 32823491, 2020). "IL-6, TNFα and B lymphocytes have been reported to play a crucial role in the inflammatory cascade taking place days before the manifestation of the most severe forms of SARS-CoV-2 infection, as well as in the physiopathological processes leading to rheumatoid arthritis." (PMID 33519443, 2020). "In addition, anti-inflammatory properties of pristimerin included inhibition of inflammatory cytokine levels (e.g., IL-6, IL-17, IL-18, and IL-23), increase IL-10 expression, and mitigate NF-κB and MAPK signaling, showed during rheumatoid arthritis model and murine macrophages exposed to LPS." (PMID 32235333, 2020). "IL-6, as a pro-inflammatory cytokine, has been proposed to contribute to the progression of rheumatoid arthritis and Crohn's disease, while SOCS3 is a major negative regulator of the IL-6-related cytokine-STAT3 pathway and enhanced expression of SOCS3 inhibits these inflammatory responses." (PMID 33281724, 2020). "Likewise, two previous systematic reviews reported that null findings of replicated effects of MBIs were observed for inflammatory cytokines in blood, including IL-6 and TNF-α, in participants with cancer, ulcerative colitis or rheumatoid arthritis, or in dementia caregivers and healthy controls." (PMID 32260096, 2020). "For example in rheumatoid arthritis, DNA methylation at an IL6-related CpG was altered in affected patients, and a negative relationship between DNA methylation and IL6 mRNA levels was observed, suggesting a DNA methylation-dependent regulation of IL6 transcription." (PMID 30795743, 2019). "Furthermore, clonal deletion of activated T cells was altered and these chronically activated T cells showed persistent IL-6-induced STAT3 and JAK1 phosphorylation indicating that IL-6 signaling in T cells plays a critical role in disease progression of rheumatoid arthritis." (PMID 31694340, 2019). "Local ice cryotherapy significantly reduced the IL-6, IL-1β, VEGF, NF-kB-p65, and PG-E2 synovial levels, especially in the microcrystal-induced arthritis subgroup, while only phosphorylated NF-kB-p65 significantly decreased in rheumatoid arthritis and spondyloarthritis patients." (PMID 31362785, 2019). "Rheumatoid arthritis (RA) is a progressive and debilitating disease characterized by an inflammatory pannus whose growth is stimulated by TNF and IL-6." (PMID 32232095, 2019). "Pro-inflammatory cytokines, like IL-6, IL-8, IL-18 and TNF are involved in the inflammatory process of autoimmune diseases, such as rheumatoid arthritis (RA) and SLE." (PMID 31195707, 2019). "This might also apply to the origin of the cells, as a prior study in fibroblast-like synoviocytes derived from rheumatoid arthritis patients found that IL-6 protein and mRNA for MMP-9, but not other MMPs, were upregulated by LIGHT." (PMID 29616048, 2018). "Given the incidence of rheumatoid arthritis in the population, and overlap of patients with both arthritis and MGUS, it may be possible to mechanistically evaluate the impact of IL-6 antibody therapy in a patient population for whom treatment is already indicated." (PMID 30453544, 2018).